TLR4 (toll like receptor 4)
Diseases named in the same sentence as TLR4 in open-access papers (continued):
Sharing a sentence is not in itself a finding about the gene and the disease.
E. coli infection (43 papers, 2008 to 2026). "In contrast to our findings, the TLR2 study revealed that TLR4-deficient mice were more susceptible to meningitic E. coli infection." (PMID 40821830, 2025). "The results showed that E. coli infection in mice activated the TLR4/MyD88/NF-κB signaling pathway, but mice pretreated with 4-PBA did not obviously activate the TLR4/MyD88/NF-κB signaling pathway." (PMID 40076603, 2025). "These analytical results mutually corroborate, collectively delineating a comprehensive molecular map of E. coli infection: LPS activates the NF-κB pathway via TLR4, which leads to the massive secretion of pro-inflammatory cytokines and chemokines." (PMID 40771952, 2025). "Partially ameliorated MDR-E. coli infection by reducing the inflammatory response through inhibiting the pro-inflammatory cytokines and strongly regulated the TLR4 signaling pathway." (PMID 39682959, 2024). "Our previous investigations have demonstrated that systemic E. coli infection in mice activates the TLR4-extracellular signal-regulated kinases 1 and 2 (ERK1/2) pathway in marrow SPCs." (PMID 38665923, 2024). "Results showed that SEP promoted bacterial clearance by enhancing phagocytosis by macrophages during E. coli infection in vitro, but was inhibited by TLR4 specific inhibitor TAK-242, STAT3 inhibitor Stattic or blockade of CD64." (PMID 35370674, 2022). "Mice that exclusively express TLR4 on ECs (ECTLR4 mice) can also detect and clear intraperitoneal E. coli infection as rapidly as wild-type mice, indicating that the endothelial TLR4 can sense and clear intravascular infection." (PMID 35678679, 2022). "In this study, SEP activated TLR4 signaling pathway and markedly protected against E. coli infection, improved bacterial clearance and attenuated systemic cytokine production." (PMID 35370674, 2022). "Pretreatment with three different doses of L. plantarum 17–5 significantly reduced the expression of TLR2, TLR4 and MyD88 mRNA after E. coli infection (P < 0.05)." (PMID 35764986, 2022). "During systemic Escherichia coli infection, stimulation of TLR4 mobilizes CD150+CD48−Lineage−/lowSca1+cKit+ hematopoietic stem cells (HSCs) to the spleen to give rise to neutrophils, which contributes to the host defense." (PMID 33763386, 2021). "After E. coli infection, the mRNA level of TLR4 increased in both groups but remained significantly higher in the TG group." (PMID 33966642, 2021). "Prior to western blotting, TLR4-overexpressing monocytes were pretreated with either dasatinib (an Src inhibitor), filipin (a strong caveolae-mediated endocytosis inhibitor), or TAK242 (a TLR4 inhibitor) and subjected to 30 min of E. coli infection." (PMID 33966642, 2021). "Reproductive tract immune responses to E. coli infection require the binding of lipopolysaccharide from E. coli to toll-like receptor 4 on the surface of epithelial cells, which then produce IL-6." (PMID 30923927, 2019). "Recent studies in DCs demonstrated a role for siglec-E in promoting TLR4 endocytosis and downregulating TLR4-mediated inflammatory responses following E. coli infection." (PMID 29379501, 2017). "We also showed that single and multiple SNPs mostly suppressed TLR4 promoter activity in vitro and especially the response to E. coli infection." (PMID 20505764, 2010). "Under Shiga toxin-producing E. coli infection, monocytes may initially bind to Stx2 through TLR4 in the infected intestinal region." (PMID 39871175, 2025). "Moreover, in response to uropathogenic Escherichia coli infection, TLR4 and TLR5 together trigger epididymal innate immune responses." (PMID 37152990, 2023). "We found that E. coli–induced an up-regulation of Tlr4 in PMECs at 6 h after E. coli infection." (PMID 32823867, 2020). "The results showed that astragalin and CGA could inhibit the progress of the inflammatory response of SEECs induced by E. coli infection via a mechanism related to the inhibition of the TLR4/NF-κB signaling pathway." (PMID 32426380, 2020).
E. coli infection (continued). "Therefore, we concentrated on E. coli-infection and TLR4-mediated signaling for the subsequent experiments." (PMID 30042932, 2018). "In addition, the blockade of TLR2 and TLR4 with the mAbs T2.5 and 1A6, respectively, prevented otherwise fatal shock in experimental Salmonella enterica or Escherichia coli infection models." (PMID 26147469, 2015). "The results indicate that TLR4 promoter variation may influence the mucosal response to E. coli infection." (PMID 20505764, 2010). "The expression of TLR4, CD14 and MD-2 (encoding MD-2 protein; alternatively known as LY96 encoding Lymphocyte antigen 96 protein) was examined next because E. coli infection is particularly important after parturition and paves the way for other pathogens to cause uterine disease." (PMID 19476661, 2009). "In the present study, E. coli infection activated NF‐κB predominantly through upregulation of TLR4 and accumulation of ROS, rather than through increased I‐κB phosphorylation, leading to elevated production of IL‐6 and TNF‐α." (PMID 41502826, 2026). "Although our study demonstrates increased IAP expression following E. coli infection, we did not evaluate TLR4 expression, proinflammatory cytokines (e.g., IL-6 and TNF-α), or NF-κB activation." (PMID 40804973, 2025). "The phagocytosis-promoting receptors were upregulated after E. coli infection, including complement receptor (CR1, CR3, and iC3b), integrins (αMβ2, αVβ3, and αVβ5), toll-like receptor (TLR2, TLR4, and TLR6), might accelerate the phagosome maturation." (PMID 36411420, 2023). "In this study on E.coli induction of GMECs, TLR4, TRAF3 and TRAF6 are significantly overexpressed as compared to the non-induced cells and the PPI network also suggests the key role of TLR4 and TRAF6/3 in the E. coli infection." (PMID 36604713, 2023). "All these data above suggested that SEP should be a mild TLR4 agonist protecting against E. coli infection rather than organ injury." (PMID 35370674, 2022). "The expression of TLRs in BF of chicks treated with HQD were up-regulated, indicating that HQD regulates the anti-infection ability by increasing the mRNA levels of TLR4, -5 and -15, further decreasing the serum LZM and IL-1β, TNF-α, IL-10, IL-6 level of chicks suffered E. coli infection." (PMID 36198724, 2022). "And in the present study, E. coli infection induced inflammatory response via activating the TLR4/NF-κB signaling pathway, and astragalin and CGA inhibited the inflammatory progress by means of reducing the expression of TLR4." (PMID 32426380, 2020). "There were no significant changes in Tlr4 mRNA expression of PMECs at 3 h after E. coli infection or L. johnsonii L531 pretreatment." (PMID 32823867, 2020). "However, several known E. coli infection pathways, such as the TLR4 and NF-κB pathways, were not enriched in our study, which is inconsistent with the results of the previous studies." (PMID 35498757, 2022).
glaucoma (43 papers, 2012 to 2025). Increased pressure in the eyeball due to obstruction of the outflow of aqueous humor. "With regard to TLR4 and glaucoma, it has been reported that a single nucleotide polymorphism in the TLR4 gene is associated with normal tension glaucoma and primary open-angle glaucoma." (PMID 38983051, 2023). "For each of the 4 clusters, notable genes associated with glaucoma, neuroinflammation, or reactive astrocytes were: Cluster 1 (Nrf2, Hspb1, S100β), Cluster 2 (Ptgs2, Clcf1), and Cluster 4 (C2, Tlr4, Lcn2, H2-T23, Thbs1, Il6ra)." (PMID 37759301, 2023). "The relationship between TLR4 polymorphisms and glaucoma has been the subject of numerous case-control investigations over the past few decades, but the results have been conflicting in some cases." (PMID 36674680, 2023). "Meanwhile, TLRs pathway induce glaucomatous neuroinflammation in two ways, either through polymorphism of TLR4 alleles or increase in TLR4 protein expression in the retina of glaucoma animal models." (PMID 35778750, 2022). "More specifically, primary open-angle glaucoma is associated with inflammation-related genes such as toll-like receptor 4 (TLR4) rs4986791 and rs2149356 and interleukin (IL)-10 rs1800871 and rs1800872." (PMID 33114701, 2020). "Our meta-analysis was based on systematic collected studies relating to TLR4 gene polymorphisms and glaucoma." (PMID 30877182, 2019). "To date, several positions of TLR4 polymorphisms have been examined for proposal as risk or protective factors of glaucoma." (PMID 30877182, 2019). "A meta-analysis was applied to calculate the pooled odds-ratio and 95% confidence intervals (CIs) to evaluate the association between TLR4 polymorphism and glaucoma." (PMID 30877182, 2019). "In the past decades, several case-control studies varying in design, ethnicity, and sample size are examining the potential association between TLR4 polymorphisms and glaucoma, only to find inconclusive or contradictory results." (PMID 31428642, 2019). "Previous studies have indicated that in some populations, the increased risk of glaucoma is associated with certain alleles of the TLR4 gene." (PMID 31737079, 2019). "TLR4 has been demonstrated to affect the risk of various multifactorial disorders, such as retinal ischemia/reperfusion injury, glaucoma, and diabetic retinopathy." (PMID 31428642, 2019). "The aim of the present study was to identify the association between TLR4 polymorphism and glaucoma (POAG and NTG) via the use of a comprehensive review and meta-analysis." (PMID 30877182, 2019). "To solve this, we applied a comprehensive review and meta-analysis between genetic models of TLR4 polymorphism and glaucoma." (PMID 30877182, 2019). "A growing body of studies have reported that TLR4 has also been implicated in the pathogenesis of glaucoma." (PMID 31737079, 2019). "Altogether, the results suggest that the TLR4 polymorphism (rs1927911, rs12377632, and rs2149356) is related to glaucoma in both POAG and NTG." (PMID 30877182, 2019). "Retinal microglia upregulate TLR expression as an early response to glaucomatous damage, polymorphisms in both TLR2 and TLR4 are risk alleles for glaucoma, and deletion of Tlr4 in mice reduces RGC death after optic nerve damage and ischemia-reperfusion." (PMID 27126275, 2016). "Here, we focused on the effect of AIBP on TLR4-associated lipid raft formation in glaucoma." (PMID 38275823, 2024). "Importantly, Tlr4 gene polymorphisms are associated with primary open angle glaucoma in multiple patient populations, and TLR4 pathway-related genes are differentially expressed in the retina and ONH of glaucomatous patients versus healthy patients." (PMID 37686046, 2023). "Additionally, TLR4 polymorphisms are indicated to be involved with slower responses to infection, reduced autoimmunity, and glaucoma." (PMID 35912101, 2022). "In addition, certain alleles of the TLR4 gene are associated with an increased risk of glaucoma in some populations." (PMID 36911656, 2022).
glaucoma (continued). "Importantly, TLR4 gene polymorphisms have been associated with enhanced glaucoma risk in some populations." (PMID 36911656, 2022). "Several polymorphisms have been identified in TLR4 in human SNP studies of glaucoma patients." (PMID 32555351, 2020). "In conclusion, this meta-analysis represented a significant correlation between TLR4 polymorphisms and both types of glaucoma suggesting that TLR4 might be involved in the pathogenesis of glaucoma and may be applied as a genetic marker for disease screening." (PMID 30877182, 2019). "Finally, the source of heterogeneity was excluded from the meta-analysis resulting in TLR4 polymorphism association with glaucoma." (PMID 30877182, 2019). "Moreover, additional factors may affect the results, such as co-segregation events whereby our meta-analysis cannot assess the haplotype between TLR4 polymorphisms and glaucoma." (PMID 30877182, 2019). "Using the microbead-induced mouse model of glaucoma, we also show an induction of genes associated with each of these pathways at 4 weeks post-microbead injection, specifically C3 and C1Q (complement cascade), TLR4 (Toll-like receptor pathway), TNFα (TNFα pathway), and NLRP3 (inflammasome pathway)." (PMID 31570110, 2019). "However, the functions of TLR4 polymorphisms in the glaucoma model are unidentified." (PMID 30877182, 2019). "Therefore, inhibiting TLR4-NF-κB-mediated release of pro-inflammatory cytokines caused by microglial activation would be an effective therapeutic approach to prevent the apoptotic RGCs in glaucoma." (PMID 27756890, 2016). "The aim was to analyze the association of the TLR2 (rs5743708), TLR3 (rs3775291), TLR4 (rs4986790, rs4986791) and TLR6 (rs5743810) polymorphisms with primary open-angle glaucoma in patients of Western Siberia." (PMID 40144379, 2025). "Pharmacologically, the TLR4/NF-κB signaling pathway is also inhibited by minocycline, and minocycline upregulates pro-survival genes in glaucoma." (PMID 40722741, 2025). "With respect to the TLR pathway our results showed upregulation of TLR4 which has also been shown to play a role in fibroblast activation and in glaucoma." (PMID 38990974, 2024). "Previous studies demonstrated that TLR4-dependent signaling activation induced microglial activation and led to RGC loss in experimental glaucoma." (PMID 38275823, 2024). "It has also been observed that Tenascin C, which is one of the ligands for TLR4, undergoes increased expression both in human glaucoma patients and in animal models." (PMID 38562304, 2024). "The first concept is that extracellular AIBP selectively reduces pathological lipid raft content in TLR4-expressing retinal glial cells, inhibiting TLR4-mediated inflammation and mitochondrial dysfunction in glaucoma." (PMID 38275823, 2024). "Notably, the remarkable selectivity of AIBP toward TLR4-associated lipid rafts and regulation of mitochondrial dynamics and function may contribute to developing a new therapeutic strategy for the treatment of glaucoma." (PMID 38275823, 2024). "S100A9 has also been reported to regulate TNFα production by activating the TLR4 pathway in acute herpetic neuralgia, a possible target for glaucoma therapy." (PMID 39125762, 2024). "We have reviewed the proposed functions of AIBP in protecting against the development of glaucoma, from inhibition of TLR-mediated inflammation via disruption of TLR4-associated lipid rafts to the regulation of mitochondrial function to NAXE activity." (PMID 38275823, 2024). "Collectively, AIBP deficiency potentially plays a role in triggering retinal glial activation and advancing TLR4/IL-1β-induced neuroinflammation, exacerbating glaucoma progression and visual dysfunction." (PMID 38275823, 2024). "The knock-out of tenascin-C was able to inhibit both microgliosis and astrogliosis in a mouse model of glaucoma, indicating its ability to act upon both of these cell types through TLR4 signaling." (PMID 37686046, 2023).
glaucoma (continued). "It has been reported that administration of LPS in an experimental animal model of glaucoma worsened RGC damage through microglial activation mediated through TLR4 signaling and complement upregulation." (PMID 38983051, 2023). "These activated myeloid cells have further been shown to up-regulate Toll-like receptor 4 (Tlr4) in glaucoma, suggesting a role for NF-κB-mediated inflammation in disease pathogenesis." (PMID 36779012, 2023). "We also demonstrate an increase in the FN-EDA isoform, a known DAMP and activator of TLR4, in the LC region of human glaucomatous donor eyes compared to normal non-glaucoma control donor eyes." (PMID 36911656, 2022). "TLR4 expression is increased in glaucoma, TGFβ-TLR4 crosstalk is involved in production of ECM and regulation of IOP, whereas a mutation in TLR4 inhibited TGFβ2-induced ocular hypertension in mice." (PMID 35432302, 2022). "Studies of anatomy have reported elevated levels of TLR2, TLR3, and TLR4 in microglia and astrocytes in the retina of glaucoma patients." (PMID 34561506, 2021). "Toll-like receptor 4 (TLR4) is reported to be upregulated in human glaucoma, and the glaucomatous retina stress possibly initiates the immunostimulatory pathway via glial TLR4." (PMID 31737079, 2019). "Furthermore, patients with glaucoma exhibit increased TLR4 expression, particularly in retinal microglia cells." (PMID 39726974, 2024). "However, the pathophysiological mechanisms of cholesterol efflux in glaucoma progression and how AIBP regulates retinal cholesterol metabolism and TLR4-associated lipid raft formation remain to be explored." (PMID 38275823, 2024). "Results from in vivo investigations suggested that blocking TLR4 signaling could be a useful strategy for treating glaucoma." (PMID 36674680, 2023). "TLR4, which is expressed by RGCs and other retinal cells, responds to a variety of endogenous ligands, which can be found in the AH and vitreous humor (VH) of individuals with retinal ischemia disorders and glaucoma." (PMID 36674680, 2023). "Very few glaucoma-related neuroinflammatory and reactive astrocyte genes and pathways were differentially expressed (Hsp70, Hsp90, Hspb1, C2, Tlr4, S100b, Lcn2, H2-T23), and understanding their significance to an overall neuroinflammatory astrocyte requires more focused functional testing." (PMID 37759301, 2023). "We also found clear up-regulation of TLR4 in glaucoma patients, which seemed to be a major regulator of chronic inflammation and inflammation-related diseases; its downstream signaling with the nuclear factor-κβ (NF-κβ) is critical for the expression of inflammatory cytokines." (PMID 38254630, 2023). "TLR4 is a relevant pathway to study in the context of glaucoma." (PMID 32555351, 2020). "Additionally, key mediators of the Toll-like receptor pathway, inflammasome pathway, and complement cascade that have been identified in human and experimental glaucoma were also examined, specifically TLR4, NLRP3, and complement components C3 and C1Q." (PMID 31570110, 2019). "Furthermore, results from in vivo treatment experiments suggested that inhibition of TLR4-NF-κB pathways would be an effective approach to prevent the apoptotic cascade of RGCs in glaucoma." (PMID 31428642, 2019). "TLRs are important contributors to the innate immune system and imbalance of both proapoptotic and protective regulation may lead to the degeneration of the RGCs in glaucoma, especially TLR4." (PMID 31428642, 2019). "Therefore, we aimed to investigate the possible association between TLR4 polymorphisms and OAG using a meta-analysis approach, followed by stratification analyses according to ethnicity and the subtype of glaucoma." (PMID 31428642, 2019). "In in vivo studies, the results suggested that the inhibition of TLR4 signaling might be a promising candidate for the treatment of glaucoma." (PMID 31428642, 2019). "We provide evidence that TLR4 signaling is involved in glaucoma development." (PMID 29109681, 2017).